ETV4 (ETS variant transcription factor 4)
Diseases named in the same sentence as ETV4 in open-access papers (continued):
Sharing a sentence is not in itself a finding about the gene and the disease.
prostate (3 papers, 2015 to 2025). "ETV4 overexpression has been implicated in prostate carcinogenesis through the induction of EMT and cell proliferation." (PMID 40469297, 2025). "In summary, this study provides new information on the oncogenic role of ETV1 and ETV4 in prostate carcinogenesis by looking at a co-expression cellular context in vitro." (PMID 25595908, 2015). "Although this cell line was not included in our initial panel, it could be a valuable model to study the individual role of ETV4 overexpression in prostate carcinogenesis, which led us to acquire DU-145 from DSMZ and perform qRT-PCR and western blot for both ETS." (PMID 25595908, 2015). "Considering the co-overexpression of ETV1 and ETV4 in MDA-PCa-2b and PC3 cells, we sought to dissect the role of these ETS in prostate carcinogenesis." (PMID 25595908, 2015). "The low frequency of rearrangements involving ETV4, ETV5 and FLI1 (less than 2%), and the lack of cell line models harboring rearrangements of these ETS members, resulted in scarce knowledge of their oncogenic roles in prostate carcinogenesis." (PMID 25595908, 2015).
benign tumors (2 papers, 2008 to 2024). "Within 17q, the genes topoisomerase II-α (TOP2A), ets variant gene 4 (E1A enhancer binding protein, E1AF) (ETV4) and baculoviral IAP repeat-containing 5 (survivin) (BIRC5) showed increased expression in all samples compared to two benign tumors." (PMID 18522746, 2008). "TOP2A, ETV4 and BIRC5 showed increased expression in all MPNST samples compared to the benign tumors, in most cases more than 20-fold, whereas HOXB7 showed approximately similar expression levels in the MPNSTs and the benign tumors." (PMID 18522746, 2008). "ETV4 showed the highest level of expression; its expression was more than 140-fold higher in MPNST9x and more than 90-fold higher in MPNST1 compared to the benign tumors." (PMID 18522746, 2008). "TOP2A, ETV4 and BIRC5 showed increased expression in all MPNST samples, in most cases more than 20-fold, whereas HOXB7 showed approximately similar expression levels in the MPNSTs and the benign tumors." (PMID 18522746, 2008).
infection (2 papers, 2017 to 2025). The state of being infected such as from the introduction of a foreign agent such as serum, vaccine, antigenic substance or organism. "Analysis of gene set enrichment revealed common pathways influenced by ETV4, including the innate immune system, MAPK signaling pathway, metabolism, biological oxidations, and pathogen infection." (PMID 40469297, 2025).
CNS tumor (1 paper, 2025). "In addition, we suggest the following diagnostic criteria: a mesenchymal high‐grade primary CNS tumor having a predominant pattern of small round cell morphology; AND INI1 and BRG1 retained expressions; AND ETV4 expression; AND the presence of a CIC or ATXN1 fusion." (PMID 39442927, 2025).
digestive tumors (1 paper, 2025). "Knockdown of ETV4 in digestive tumors inhibited cell proliferation and migration, promoted apoptosis, and altered the expression of immune-related molecules." (PMID 40469297, 2025).
metabolic disease (1 paper, 2025). A congenital disorder (due to inherited enzyme abnormality) or acquired (due to failure of a metabolically important organ) disorder resulting from an abnormal metabolic process. "Notably, phenome-wide association studies (PheWAS) of Etv4 revealed a significant number of genomic variants associated with metabolic traits (P-value < 0.01), suggesting its involvement in metabolic diseases." (PMID 40324882, 2025).
ETV4 also shares sentences with these, for which no sentence is quoted: neuroblastoma (4 papers); esophageal cancer (3); acute myeloid leukemia (2); cholangiocarcinoma (2); colorectal mucinous adenocarcinoma (2); infertile (2); lung squamous cell carcinoma (2); metastatic melanoma (2); osteoarthritis (2); renal cell carcinoma (2); adult onset asthma (1); brain cancer (1); breast adenocarcinoma (1); cardiovascular disease (1); Cerebral ischemia (1); cleft palate (1); cognitive disorder (1); digestive system carcinoma (1); endocervical adenocarcinoma (1); head and neck squamous cell carcinoma (1); hypoglycaemia (1); Insulin resistance (1); intestinal cancer (1); intestinal disease (1); intestinal tumors (1); intrahepatic cholangiocarcinoma (1); invasive carcinoma (1); invasive ductal carcinomas (1); kidney chromophobe (1); leukaemia (1).
A further 24 diseases each share a sentence with ETV4 in 1 paper.